AKT1 (AKT serine/threonine kinase 1)
Diseases named in the same sentence as AKT1 in open-access papers (continued):
Sharing a sentence is not in itself a finding about the gene and the disease.
cancer (continued). "However, when the Akt1 activity declines as the cancers progress to the advanced stages, an increase in the miR-199a-5p expression is also expected, which is evident in Akt1-deficient PC3 and DU145 cells." (PMID 35406397, 2022). "In particular, SMYD3 methylates AKT1 at lysine 14 in cancer cells, promoting its phosphoactivation." (PMID 35495117, 2022). "Selective AKT1 inhibitor A-674563 strengthened cancer cell apoptosis compared to pan-Akt inhibitor MK-2206, which demonstrated that targeting the AKT1 isoform might be more effective than suppressing the Akt isoforms." (PMID 35646655, 2022). "Aberrant activation of the PI3K/Akt1 pathway is common in a wide range of human cancer cells." (PMID 35563814, 2022). "AKT1 is a target of different miRNAs that regulate AKT1 protein levels in cancer cells." (PMID 35269443, 2022). "Therefore, our goal is to screen out more effective AKT1 inhibitor candidates than Ipatasertib from the ZINC15 natural compound database to provide more ideas for the treatment of cancer." (PMID 35603567, 2022). "AKT1 (v-akt murine thymoma viral oncogene homologue 1) kinase is a critical protein which plays an important role in proliferation and survival pathways in cancers." (PMID 35611247, 2022). "In addition, the cancer derived mutant E17K in Akt1 was more efficiently SUMOylated than wild-type Akt1." (PMID 36180910, 2022). "Hence, it is important to profile the Akt1-regulated miRNAs in advanced cancers and study their molecular and functional implications in advanced cancers for translational purposes." (PMID 35406397, 2022). "AKT1 kinase is constitutively active in many cancers and suppression of AKT activation may attenuate cancer progression." (PMID 35273218, 2022). "When AKT1 was weakly active, it inhibited the proliferation of cancer cells in the laboratory." (PMID 36286049, 2022). "In addition, we show that the levels of Akt1 phosphorylation in cancer cells are correlated with miR-145 suppression and DNA-PKcs upregulation." (PMID 35563814, 2022). "EOC cells are a well-studied model system for AKT1-driven cancers." (PMID 35269443, 2022). "Kinase CK2 phosphorylated Akt1 at Ser129 and can also enhance cancer cell survival." (PMID 36243702, 2022). "Interestingly, despite different molecular mechanisms reported by various laboratories for this unforeseen role of Akt1 in advanced cancers, it does get reconciled at one single point, which is EMT." (PMID 35406397, 2022). "Akt1 suppression in advanced cancers has been indicated to promote metastasis." (PMID 35406397, 2022). "AKT1 was regarded as the major regulator in metabolism of cancer growth and KRAS could promote autophagy under metabolic stress." (PMID 35096270, 2022). "Targeting let-7 in EOC cells may thus be exploited to specifically target AKT1-driven cancers and reduce risks of metastasis." (PMID 35269443, 2022). "Moreover, we saw the loss of differentially transcript pairs of cancer hallmark genes including SMAD2 and AKT1 in all HCT116KO." (PMID 35552415, 2022). "Importantly, miR-145 overexpression completely restored the NHEJ activity in cancer cells transfected with the constitutively active Akt1 construct." (PMID 35563814, 2022). "In echoing this finding, depletion of either CTR1 or AKT1 both could compromise Nedd4l tumor suppressor roles in repressing cancer cell malignant phenotypes." (PMID 34278744, 2021). "AKT1 is a known oncogene which plays a direct role in cancer." (PMID 34899953, 2021). "Therefore, activation of the AKT1-CREB-PDGFRα signaling pathway contributes to the tumor growth induced by PTEN deficiency and should be targeted for cancer treatment." (PMID 33568640, 2021). "Because of the importance of the PI3K/AKT1 signaling axis in cancer proliferation and metabolism, treatments targeting the pathway could be promising." (PMID 34831420, 2021).
cancer (continued). "Moreover, HRDetect-low cancers were enriched for PI3 kinase/AKT1 pathway abnormalities, indicating potentially actionable targets for further treatment." (PMID 34888495, 2021). "In addition, more evidence has indicated that Akt2 and Akt3 isoforms are more frequently amplified than Akt1 in cancer disorders." (PMID 34439105, 2021). "In the four cancer types, AKT1 was identified as a potential drug target." (PMID 33917859, 2021). "AKT1, which regulates many cellular processes in cancers, including metabolism, proliferation, cell survival, growth, and angiogenesis, may serve as a potential biomarker for the prediction of prognosis for patients and the identification of high-risk cases." (PMID 33917859, 2021). "Our data also show that the acidic bile‐induced Akt1 overexpression, a frequent event in human cancers including head and neck, can be successfully inhibited by post‐treatment or simultaneous co‐administration of curcumin with acidic bile compared to its pre‐treatment." (PMID 32691972, 2020). "The results suggested that compounds 4 and 9 could be used as drug candidates for cancer therapy via its potential inhibition of AKT1 as described by docking study." (PMID 33080996, 2020). "The PI3K/AKT1 pathway is one of the most commonly deregulated pathways in human cancer." (PMID 33614606, 2020). "The AKT1 gene goes out of control in many cancers and plays a central role in the PI3K pathway." (PMID 32005873, 2020). "The analysis of single nucleotide polymorphisms (SNPs) of AKT1, an isoform of AKT, and LMTK3 is only a beginning of the molecular pathogenesis understanding and the revelation of mechanisms leading to susceptibility to cancer." (PMID 33247671, 2020). "Design studies of the 3D structure and LMTK3 and AKT1 inhibitors may be useful to block the spread of cancer in patients with CRC." (PMID 33247671, 2020). "Among these three isoforms, Akt1 shows overexpression in various cancers including GCTB." (PMID 32351329, 2020). "In summary, the results indicated that the quinazolinone derivatives could be used as potential inhibitors for cancer treatment via AKT1 inhibition." (PMID 33080996, 2020). "Their continual activation may lead to the development of cancer phenotype, while Akt1/2 knockout mice, which have dwarfism and skin, muscular, and bone atrophy, die immediately after birth." (PMID 33224432, 2020). "The mechanism may be related to Leptin/STAT3 signal transduction, VEGF-A, VEGFR-1 and WCAF target proteins related to cancer immune such as leptin and AKT1." (PMID 33746736, 2020). "Besides, correlation analysis showed MYC, AKT1 mRNA expression and glycolysis score were positive correlated across a variety of cancers ranging from r = 0.10 to 0.57 for MYC and r = 0.15 to 0.50 for AKT1 (p < 0.05)." (PMID 32635458, 2020). "The gene network of AKT1/mTOR signaling pathway plays a crucial role in cancer development." (PMID 33247671, 2020). "In addition, cancer cells overexpressing lysine 14-substituted AKT1 shows decreased growth rate in comparison to those overexpressing wild-type AKT1." (PMID 31935919, 2020). "A total of 155 nodes, including 20 putative targets of HZJD decoction, were selected as core hubs based on topological importance and were closely associated with the regulation of cell proliferation, apoptotic process, and cancer-related pathways (AKT1, TNF, VEGFA, and EGFR) in CAG." (PMID 33354218, 2020). "Reports show that interaction between FAK and Akt1 is found in many cancers." (PMID 31886261, 2019).
cancer (continued). "Gene expression analysis revealed that its mechanism of action might be attributed, in part, to downregulation of cancer-related genes, such as AKT1, BCL2L1, CCND1, CDK4, PLK1, and RHOA." (PMID 31527550, 2019). "In human cancers, AKT1 plays a central role in tumorigenesis." (PMID 31781484, 2019). "Many researchers have reported the regulatory role of miR-149-5p on AKT1 in other cancers." (PMID 30717751, 2019). "Additionally, Akt1 appears to be robustly involved in the tumourigenesis and invasion of cancer cells." (PMID 30872976, 2019). "Indeed, activation of mutated KRAS cancer cells is highly dependent on RAD51 for survival, KRAS mutation-dependent AKT1 stimulates HR and NHEJ activities for DNA DSB repair, and nuclear translocation of EGFR is associated with DNA-PKs for DSB repair." (PMID 31554189, 2019). "However, it is well-known that Akt kinase exists in three different isoforms as Akt1, Akt2, and Akt3, and these display distinct functions in various cancers." (PMID 31252679, 2019). "However, it has three isoforms (Akt1, Akt2, and Akt3) and they perform distinct functions and even play contrasting roles in different cancers." (PMID 31252679, 2019). "AKT1 is known to promote survival and proliferation of various cancers." (PMID 30943211, 2019). "Moreover, silencing of Akt1 and 2 isoforms was found to decrease the expression of proteins regulating cancer cell survival and proliferation such as cyclooxygenase-2, B-cell lymphoma 2 (Bcl-2), cyclin D1, and survivin." (PMID 31252679, 2019). "In addition, many studies have demonstrated the role of Akt1 in metastases development in several malignancies, such as colorectal and lung cancers." (PMID 30647870, 2018). "Moreover, the miR-302-367 cluster was reported to directly downregulate both AKT1 and cyclin D1, and indirectly upregulated p27Kip1 and p21Cip1, leading to the suppression of cancer cell proliferation, which is accordance with our data." (PMID 30326936, 2018). "Combined, these results suggest that AKT1 and AKT2 may play opposite roles in the metastatic process and that differential AKT isoform activities require further consideration in cancer studies." (PMID 29506489, 2018). "Different cancer lineages displayed differential AKT1 and AKT2 expression and phosphorylation." (PMID 30012111, 2018). "While, HSP90 is up-regulated in many diseases including cancer, treatment with HSP90 inhibitors evoked dissociation of HSP90 from phosphorylated Akt1 and subsequent degradation, highlighting a new potential therapeutic target for the treatment of cancer with up-regulated Akt activity." (PMID 29562639, 2018). "Our study suggests that the repressive action of PI3K/AKT1 on cellular invasive properties may be a mechanism common to several cancers." (PMID 29506489, 2018). "The Akt1 isozyme has well-established roles in many human cancers." (PMID 30205513, 2018). "In short-term experiments (minutes to hours), Akt1 phosphorylation reduced in response to inhibitor treatment, but at longer times (2–3 days) Akt1 phosphorylation status returned to stimulated levels in these cancer cells." (PMID 30205513, 2018). "Likewise, carriers of 11 SNPs in the IRS1 and AKT1/2 genes (signaling pathway–related genetic variants) had different associations with CRC risk between strata, and the proportion of the SNP–cancer association explained by traits varied from 30% to 50%." (PMID 29023587, 2017). "Akt1 among other subtypes of Akt (Akt2 and Akt3) is involved in various cancers." (PMID 29088809, 2017). "For AKT1 rs2494750 polymorphism, we have not found the correlation with the cancer susceptibility both in overall analysis and subgroup analysis." (PMID 29259266, 2017). "Like MMP2, PIK3CA and AKT1 play important roles in cancer cell migration and metastasis." (PMID 29322935, 2017). "Moreover, ∆Np63α enhances the expression and activation of Akt1 and p-Akt1 which preferentially induces the proliferation and survival of cancer cell." (PMID 28137308, 2017).
cancer (continued). "In this study, estrogen and progesterone receptor positive (ER + /PR + ) IBH-6 and T47D cancer cells were stably modified to upregulate or downregulate specifically AKT1 or AKT2 isoforms and search for their specific effects on cell proliferation, adhesion and invasion." (PMID 28287129, 2017). "Most of these mutations occur in signal transduction-related kinases, including HER2, KRAS, AKT1, MEK, and EGFR, and they cause constitutive kinase activation, thereby inducing aberrant cancer cell growth and metastasis, which lead to poor prognoses and poor patient treatment responses." (PMID 29132432, 2017). "AKT1 exhibits a cell type-specific role in regulating cell migration in different cancer cells." (PMID 28082369, 2017). "AKT1 and AKT2 are frequently activated in human cancer following loss of the lipid phosphatase PTEN, activating mutations and/or copy number variation in EGFR or HER2 tyrosine kinase receptors, activating mutations in KRAS, in PIK3CA or in AKT1 itself." (PMID 26859676, 2016). "Activation of Akt1 has been detected in approximately half of pancreatic ductal adenocarcinoma cancer patients, and it appears to exert its oncogenic activity in this cancer by overcoming cell cycle arrest, blocking apoptosis, and promoting angiogenesis." (PMID 26919188, 2016). "Furthermore, substitution of lysine 14 diminishes the plasma membrane accumulation of AKT1, and cancer cells overexpressing lysine 14-substiuted AKT1 shows lower growth rate than those overexpressing wild-type AKT1." (PMID 27626683, 2016). "Our results suggest that miR-495 could regulate the protein levels of Foxo1, p27kip1, p21Cip1, and Cyclin D1, all of these genes are downstream of Akt1, and subsequently inhibit cancer cell growth by promoting cell cycle arrest." (PMID 27323412, 2016). "Additionally, two promising anti-cancer agents targeting AKT1 (the cytotoxic alkylphospholipids Perifosine and Miltefosine) bind to the PH domain, which blocks membrane localization of AKT1 and results in a reduction in the level of AKT1 phosphorylation." (PMID 27626683, 2016). "Similar results for AKT1: rs3803300 have been observed in other cancers." (PMID 27876891, 2016). "Moreover, both AKT1 rs2294750 and AKT2 rs7254617 polymorphisms have been investigated in cancers among Chinese populations 9, 19, but results are conflicting." (PMID 26828791, 2016). "Effects of Akt1 on differentiation and invasion are now starting to emerge in a variety of cancers." (PMID 27661110, 2016). "To further explore the biological functions of SMYD3 in human cancer, we performed liquid chromatography tandem-mass spectrometry (LC-MS/MS) analysis of AKT1 protein and identified that lysines 14, 30 and 39 (Lys 14, Lys 30 and Lys 39) in the PH domain of AKT1 were possibly methylated by SMYD3." (PMID 27626683, 2016). "The PDK1 substrates Akt1, Akt2, and Akt3 are highly expressed in several types of human cancers." (PMID 26318166, 2015). "In addition, introduction of cells with constitutively active AKT1 significantly rescued the inhibitory effect of RY-2f, clearly indicating that the anti-cancer effect is dependent on suppression of the PI3K/AKT /mTOR pathway." (PMID 26325371, 2015). "For example, AKT1 is an important oncogene and plays a critical role in many cancer types." (PMID 25360158, 2014). "For example, several investigational drugs, such as MK-2206 and GDC-0068, inhibit AKT1 and clinical trials with these agents may be treatment options to consider for cancers with activating AKT1 aberrations." (PMID 25593991, 2014). "Furthermore, down-regulation of HSP90AA1 led to the degradation of its client proteins (PIM1 and AKT1), which are also cancer therapy targets." (PMID 25167922, 2014).
cancer (continued). "The PI3K/AKT1/mTOR pathway was related to the cancer call metastasis and proliferation." (PMID 24757677, 2014). "Akt1 phosphorylates the human and mouse p21 protein at the same locus (T145, S146 in human cells; T140, S141 in mouse cells), thereby stabilizing the protein and localizing it to the cytoplasm in a variety of human cancer cells and in TGCs (this report)." (PMID 24848107, 2014). "Akt1 might indeed be a candidate therapeutic target in cancer cachexia and even survival of PDAC, after the selection of the patients according to their genotype." (PMID 25238546, 2014). "However, Akt1-dependent cytoplasmic localization of p21 occurs in a variety of cancers where it promotes tumorigenesis by inhibiting proteins essential for apoptosis." (PMID 24848107, 2014). "Constitutive activation of Akt1 kinase occurs in human cancer through deletion and mutation of the tumor suppressor gene PTEN, the phosphatase that negatively regulates Akt1, through amplification of the Akt1 genes, or through amplification of the catalytic subunit of PI3 kinase." (PMID 24658544, 2014). "PI3K activation, e.g., by activating mutations of PIK3CA encoding the catalytic subunit, p110alpha, leads to an activation of AKT, a serine-threonine kinase, which is present in three different isoforms (AKT1-3) in human cancer and leads to increased cellular growth and survival of cancer cells." (PMID 24036443, 2013). "Furthermore, AKT1-expression was reduced, being known for central roles in proliferation and survival pathways in cancer." (PMID 23969837, 2013). "Akt1 is a pro-survival protein with a well-established role in the biology of cancer." (PMID 22776333, 2012). "Moreover, P-Rex1 had an important role in the activation of AKT1 and in mTORC2/AKT1 signaling, thereby contributing to cancer cell migration." (PMID 22680924, 2012). "mTORC2 also was shown to regulate cancer cell migration through selective activation of AKT1." (PMID 22680924, 2012). "Since AKT and Rac1 require each other for their activation, our findings suggest that loss of miR-204 expression in human tumors may induce the positive feedback loop between BDNF/AKT1/mTOR and Rac1 during cancer cell migration and invasion." (PMID 23285024, 2012). "Mutations of AKT2 have been sporadically reported in various human cancers, but none of these mutations occur at the corresponding position of the E17K in AKT1." (PMID 22666248, 2012). "Nuclear Akt1 staining was present in 52% (76/147) of cancers." (PMID 21407808, 2011). "Furthermore, it provides the rationale for the development of specific Akt1 inhibitors as efficient anti-cancer therapeutic agents." (PMID 19549334, 2009). "Oncogenes such as MYC, AKT1, AKT2, cyclins CCNA2, CCNB1, CCNB2, CCNE1, CCNE2 and cyclin-dependent kinases CDK1 and CDK4, which were upregulated under androgen treatment, exhibited a significantly reduced expression following PVT1 knockdown, thereby modulating cancer-associated oncogenic pathways." (PMID 41792045, 2026). "Moreover, although PKB/AKT1 is hyperactivated in a wide variety of cancers, nothing was known about whether PKB itself generates genomic instability." (PMID 40479710, 2025). "Therefore, inhibiting AKT1 activity may reduce tumor cell proliferation, promote tumor cell apoptosis, and disrupt the energy metabolism of cancer cells, thereby exerting anti-cancer effects." (PMID 39598341, 2024). "Furthermore, the expression level of AKT1 was observed to be insignificant in treated HeLa cells despite its crucial role in the regulation of cell survival, angiogenesis, and tumorigenesis of cancer." (PMID 39005932, 2024). "Thus, AKT1 has emerged as an attractive target for new anti-cancer therapy development." (PMID 36959600, 2023). "Therefore, in the context of genotoxicity, SGK1 may escape treatments targeting PI3K and AKT1 inhibition in cancer cells, a setting where the small survival advantage conferred by active SGK1 may prove most significant." (PMID 37343701, 2023).